SDC2 (syndecan 2)
Diseases named in the same sentence as SDC2 in open-access papers (continued):
Sharing a sentence is not in itself a finding about the gene and the disease.
tumor (continued). "The authors suggest that stromal-derived syndecan-2 influences tumor progression by modulating TGF-β signaling in the tumor microenvironment." (PMID 35378690, 2022). "The results showed that the growth factor LR interacts with PDGFB : PDGFRA, IGFBP4:FZD8, and TGFB1:SDC2 with TAMs and tumor vascular cells." (PMID 35664733, 2022). "Previous studies demonstrate that syndecan‐2 inhibition (via SDC2 knockdown or syndecan‐2‐peptide) within the epithelial compartment of tumours also reduces tumour growth and metasatasis in immune‐compromised models." (PMID 33152121, 2021). "The left‐sided tumors showed lower frequency methylation than right‐sided tumors and the rectum, indicating a highly heterogeneous methylation status of SDC2 CpG islands across different tumor locations." (PMID 33955718, 2021). "On the other hand, overexpression of SDC2 in TASCs increases TGFβ signalling within human xenograft tumours, enhancing tumour growth and metastasis." (PMID 33152121, 2021). "It has been reported that aberrant SDC2 methylation occurs frequently in the early stages of neoplasia, is maintained in advanced CRC, and is unaffected by such factors as disease stage, age, sex, and race." (PMID 33858326, 2021). "Tumours containing AdSDC2‐transduced TASCs had elevated RNA levels of SDC2, SMAD7 and PAI‐1 (P < .05)." (PMID 33152121, 2021). "In non-tumor tissues, Sdc1, Sdc2, Sdc3, Sdc4, and Sdcbp were expressed in all four prostate lobes, with no significant quantitative difference among them." (PMID 34445387, 2021). "Immune infiltration analysis showed that the expressions levels of COL3A1, RAC1, FN1, and SDC2 in CD4+T cells were significantly higher than those in tumor cells, especially regulatory T cell infiltration was significantly increased in BM tumors." (PMID 34229299, 2021). "The effect of SDC2 knock down in TASCs, by transduction with shSDC2, on tumour growth was compared to that of tumours generated with shControl‐transduced TASCs." (PMID 33152121, 2021). "Overexpression of SDC2‐peptide in TASCs resulted in significantly lower tumour volume by Day 27 compared to tumours containing control‐transfected TASCs and lower metastatic scores in the lungs." (PMID 33152121, 2021). "On the contrary, a tumor-suppressor function for SDC2 correlated to apoptosis dysregulation in osteosarcoma has been suggested." (PMID 32916872, 2020). "Recently, LMP1 has been shown to enhance EV release through Syndecan-2 and synaptotagmin-like-4 through NF-κB signaling and this promotes cell proliferation, invasion and tumor growth in vivo." (PMID 33382850, 2020). "Early stage tumors usually have smaller sizes, and the combination of methylated SEPT9 or methylated SDC2 showed a significant improvement in detecting CRC of smaller tumor sizes when compared with either biomarker alone." (PMID 31407497, 2019). "NDRG4 and SDC2 had higher frequency and level of methylation in tumors than in normal or non-tumor adjacent tissues." (PMID 31602277, 2019). "The methylation status of SEPT9, BMP3, NDRG4, and SDC2 was analyzed by using qMSP in matched patient tissue samples (n=23) from tumor, non-tumor adjacent tissue, and normal tissue." (PMID 31602277, 2019). "In CRC, the contact between cancer cells with fibronectin enhances syndecan-2 expression, promoting a migratory behavior of highly metastatic tumor cells." (PMID 30027065, 2018). "In the present study, we semi-quantified via immuno-histological analysis the levels of SDC2 protein in the same set of the tumor tissues in mice that were subjected to an injection of Dox or PBS." (PMID 29118673, 2017). "Apparently, SDC2 appears to have specific roles in bone cells but the studies of SDC2 effects with respect to tumor chemoresistance are rare." (PMID 29118673, 2017). "In tumor cells, syndecan-2 staining was cytoplasmically distributed but we also noted that some displayed nuclear staining." (PMID 25623282, 2015).
tumor (continued). "Treatment with metformin markedly suppressed PKM2 and SDC2 expression at both the transcriptional and posttranscriptional levels and inhibited HC cell proliferation and tumor growth." (PMID 26576639, 2015). "Overall, syndecan-2 indirect effect on integrin activation participates in the organization of different tissues; we will explore its role in tumor development in the following sections." (PMID 26558271, 2015). "Subcutaneous images showed an increase in photon emission from the tumor sites in syndecan-2 peptide treated mice compared with PBS treated control mice." (PMID 25686828, 2015). "Together, these in vivo results suggest that shed syndecan-2 directly plays an important role in primary tumor growth and metastasis." (PMID 25686828, 2015). "Syndecan-2 peptide significantly enhanced primary intrasplenic tumor growth, and liver metastasis of 4T1 cells." (PMID 25686828, 2015). "More importantly, syndecan-2 expression was upregulated in lymph node samples compared directly with the primary tumours and in triple negative cases, expression of syndecan-2 and caveolin-2 were correlated." (PMID 25623282, 2015). "Analogously to syndecan 2, glypican 1 expression was analyzed by immunohistochemistry using tumor tissue arrays." (PMID 24570896, 2014). "Specifically, SCID-SHO mice were injected with empty vector cells or cells that constitutively released syndecan-2 (eS2ED) and tumour sizes were quantified at 21 days." (PMID 25179601, 2014). "We demonstrate that shed syndecan-2 regulates angiogenesis by inhibiting endothelial cell migration in human and rodent models and, as a result, reduces tumour growth." (PMID 25179601, 2014). "Using these cell lines, we investigated the anti-angiogenic properties of shed syndecan-2 in a xenograft tumour model." (PMID 25179601, 2014). "CD31-positive cells were greatly reduced in tumour sections derived from cells constitutively releasing syndecan-2." (PMID 25179601, 2014). "HC11-Phf19, -Foxl and -Sdc2 cells were also injected subcutaneously into the mammary fat pad of athymic nude mice to test for their tumor inducing capability." (PMID 23131872, 2012). "This is the first report demonstrating that syndecan-1 enhances malignancy of a mesenchymal tumour cell line, via induction of syndecan-2 expression." (PMID 22745764, 2012). "Ets-1 is a potential transcription factor to IGF1R, and it is involved in tumour invasion and metastasis processes also regulated by syndecan-2 in HT-1080 cells." (PMID 22745764, 2012). "Little is known about the functions of Syndecan-2 in EOC, although it is known to be expressed in both tumor associated stroma and on the surface of epithelial cells." (PMID 22583667, 2012). "Taken together, this work is the first to present syndecan-1 playing a tumour promoter role in a mesenchymal tumour cell line, a process that progreses through the cooperation of syndecan-1 and syndecan-2." (PMID 22745764, 2012). "In a number of neoplasms, expression patterns of syndecan-1 and syndecan-2 characteristically correlate with the tumour stage and grade." (PMID 22745764, 2012). "In another type of mesenchymal tumour, osteosarcoma, syndecan-2 expression is reduced compared to that in osteoblasts and osteocytes in normal bone, and the expression of the proteoglycan sensitises tumour cells to basal and chemotherapy-induced apoptosis." (PMID 22745764, 2012). "Furthermore, comprehensive methylation analysis has unveiled aberrant methylation of CpG sites in syndecan 2 (SDC2) in tumor tissues of most CRC patients, demonstrating a huge potential for quantifying blood SDC2 methylation for early CRC detection." (PMID 38464391, 2024). "Indeed, a syndecan-2 peptide blocking syndecan-2 also decreased expression of CXCR4 and PDL-1, thereby diminishing the immunosuppressive properties of tumor-associated stromal cells." (PMID 38761292, 2024).
tumor (continued). "IHC staining of USP14 in our FUSCC cohort showed that the IHC score was significantly higher in carcinoma tissues than normal tissues, and the expression of SDC2 was significantly higher in the High-USP14 group (IHC score > 4) than the Low-USP14 group of GC tumor specimens." (PMID 37496999, 2023). "SDC2 and TFPI2 methylation, which was affected by tumor location, patient age, mutation load, and microsatellite instability (MSI), may be considered methylation markers for CRC detection." (PMID 37779184, 2023). "Indeed, both iRP-D26 and iRP-D28A showed upregulation of several genes known to facilitate human EVT and/or tumor cell invasion, including SDC2, TIMP3, MMP14, and ADAM12." (PMID 34154587, 2021). "Indeed, our data indicate limiting syndecan‐2 (by SDC2 knockdown or syndecan‐2 peptide overexpression) in TASCs attenuates TGFβ signalling within the breast TME reducing tumour growth and metastasis." (PMID 33152121, 2021). "Altered expression of syndecan-2 has been detected in several different tumours." (PMID 31738794, 2019). "In this study, we demonstrated that SEPT9, NDRG4, and SDC2 had higher frequency and level of methylation in tumors than in normal or non-tumor adjacent CRC tissues, indicating that these methylated genes may have diagnostic potential for CRC screening." (PMID 31602277, 2019). "However, it is important to note that in addition to the pro-tumorigenic effects, some HSPGs, such as SDC2, exert tumor suppressive effects depending on the cancer type." (PMID 30197623, 2018). "In this study, we used a bisulfite-pyrosequencing methylation assay on an independent group of CRC patients to confirm the high prevalence of aberrant SDC2 methylation in tumor tissues of CRC patients and precancerous biopsies with various stages compared to those of normal tissues." (PMID 29225717, 2017). "The syndecan-2/caveolin-2 relationship may provide an important insight into regulation of a specific membrane microdomain in tumour, and perhaps untransformed cells." (PMID 25623282, 2015). "Syndecan-2 expression is upregulated in colon cancer, pancreatic cancer, melanoma and fibrosarcoma where it enhances cell adhesion, proliferation and migration in cancer cells, suggesting that it is important in promoting tumor progression." (PMID 25623282, 2015). "More specifically, enhanced expression of SDC2 in the tumour stroma significantly correlates with overall survival and is indicative of lymphonodal metastasis, whereas aberrant increased of SDC1 transcription is indicative of the presence of distant metastases." (PMID 25935541, 2015). "In addition, we quantified the existence of correlations between syndecan 2 expression and tumor topography using the classical division into foregut, midgut, and hindgut, although no positive relationship was found (p = 0.85)." (PMID 24570896, 2014). "Therefore it would appear that the role that SDC2 plays is complex and depends on the type of tumor and microenvironmental factors." (PMID 24570896, 2014). "In particular, a shift from the expression of anti-tumorigenic syndecans to the tumorigenic syndecan-2 may have implications in the migratory behavior of highly metastatic tumor cells." (PMID 23705906, 2013). "Furthermore, elevated transcription and protein expression of syndecan-2 in FullEGFP and 78Sig expressing tumours was confirmed by qRT-PCR and immunofluorescent staining." (PMID 22745764, 2012). "In addition, DUSP1 and SDC2 exhibited an increase in macrophages in the tumor microenvironment." (PMID 39871942, 2024). "Moreover, the inhibition of syndecan-2 could reduce tumor cell migration, protecting CRC patients from metastasis." (PMID 30027065, 2018).
tumor (continued). "We found that in both metabolism-related pathways, SLC5A3 + tumor cells exhibit significant communication with CAFs, particularly through the FN1/SDC2, FGF7/FGFR1, NGF/SORT1, and LRPAP1/LRP1 receptor-ligand pairs." (PMID 40652057, 2025). "We then performed IHC staining to measure the expression of SDC2, p-AKT, and Ki67 in tumor samples from the xenograft models." (PMID 37496999, 2023). "In summary, the combined detection of SEPT9, SDC2, and ALX4 methylation status in plasma can cover multiple molecular pathways of tumor formation and further improvement in detection sensitivity, especially of the PL." (PMID 37881109, 2023). "The SDC2 gene, known for its high methylation level in CRC tumor tissues compared to adjacent non‐tumor tissues, has demonstrated good detection performance as a mature methylated marker for CRC." (PMID 37881109, 2023). "These analyses used our GC tumor transcriptomics data from the SYSUCC cohort, with stratification into groups that had high or low expression of SDC2." (PMID 37496999, 2023). "Specifically, genes that allow tumour cells to interact with extracellular components, such as syndecan 2 and CD36, were lower in cell lines than in tumours." (PMID 26289960, 2015). "This raised the possibility that the selection for Sdc2 and Phf19 expression during mammary tumorigenesis is a collaborative event with other MMTV activated genes in the same tumor." (PMID 23131872, 2012). "Several studies demonstrated that methylation patterns of SEPT9, SDC2, and BCAT1 in plasma (circulating tumor DNA) could distinguish CRC from benign polyps with high diagnostic accuracy (AUC = 0.914)." (PMID 41514609, 2025). "In addition to IGFBP7, the remaining differential genes (SDC2, COL8A1, IFI27, and ALDH1A1) were related to tumor drug resistance in the intersection of drug resistance differential genes." (PMID 40224214, 2025). "The zinc finger protein 625, LON peptidase N terminal domain and ring finger 2, WD repeat domain 17, and syndecan 2 CpG island promoters were methylation in both cancer and laterally spreading tumor non-granular (LST NG)." (PMID 37719843, 2023). "Western blotting showed that the protein levels of SDC2 were higher in tumor specimens than in matched adjacent normal tissues." (PMID 37496999, 2023). "However, SDC2 expression was significantly higher in normal tissues (P < 0.05), and SHOX2 expression was significantly higher in tumor tissues (P < 0.01)." (PMID 36803423, 2023). "However, there was no published information as to the source of this aberrant expression of SDC2 and TCF7L1 in tumor biopsies from patients with MESO." (PMID 35127947, 2022). "And two hypoxic genes (SERPINE1 and SDC2) were found with no obvious difference in tumor tissues and normal tissues." (PMID 36527012, 2022). "All CRC patients, who had been originally tested positive of SDC2 methylation, were tested negative after tumor resection." (PMID 33126908, 2020). "Other members of the syndecan family, such as SDC2 and SDC3, also affect tumor angiogenesis." (PMID 30197623, 2018). "SDC2 hypermethylation was in HPV-positive primary tumor of head and neck squamous cell cancer and glioma multiforme; however, details of clinical performance of SDC2 methylation test were not addressed in these studies." (PMID 29225717, 2017). "The methylation of other genes, CLIP4, XKR6, CCDC57, MAML3 and SDC2, was related with one or more of the following variables: age, tumor location, and Helicobacter pylori infection, rather than with the histologic subtype." (PMID 28418867, 2017). "The objective of this study was to confirm a high frequency of SDC2 methylation in tumor tissues at various stages of CRC and investigate the feasibility of a quantitative test for SDC2 methylation in fecal DNA by highly sensitive and accurate real-time PCR for early detection of CRC." (PMID 29225717, 2017).
tumor (continued). "In a tissue level, SDC2 methylation events have been observed in all tumor tissues of most CRC patients but have never been observed in normal colon tissues by pyrosequencing-based methylation assay having a detection limitation of 5%." (PMID 29225717, 2017). "More importantly, syndecan-2 and caveolin-2 staining were significantly elevated in cancer patient samples compared to normal tissues regardless of tumor grade." (PMID 25623282, 2015). "Additionally, MDK–NCL/SDC2/SDC4 interactions played a central role in CAF interactions with other cells, while CD99–CD99 interactions were widely involved in communications between immune cells and tumor cells." (PMID 40260248, 2025). "For example, the SDC2 (syndecan-2) protein functions as an integral membrane protein and participates in cell proliferation, cell migration and cell-matrix interactions via its receptor for extracellular matrix proteins, and altered SDC2 expression has been detected in several different tumor types." (PMID 39399221, 2024). "These in vivo studies demonstrate that stromal‐derived SDC2 regulates primary tumour growth and metastasis and modulates TGFβ signalling within the TME, suggesting that blocking stromal‐derived syndecan‐2 has the potential to inhibit tumour growth and metastasis." (PMID 33152121, 2021). "In contrast to SDC1 and SDC2, both SDC3 and SDC4 were undetectable in the healthy epithelium, or the tumour stroma, but could be immunolocalized both subcellularly and on defined portions of the cell surface of neoplastic cells, with a particular concentration in focal plaque-like structures." (PMID 25935541, 2015). "In this study, SDC2 expression was not influenced by the location of the tumor (foregut, midgut, or hindgut), suggesting that it is a common feature of these neoplasms throughout the body and that their size or spread do not significantly influence the expression of this protein." (PMID 24570896, 2014). "When the syndecan 2 semiquantitative expression levels in the different tumors were analyzed in relation to their diagnosis features, there was a significant correlation with tumor grade (r Spearman −0.47, p = 0.004) although the correlation was not significant in terms of tumor stage (p = 0.2)." (PMID 24570896, 2014). "In this study, GSL I of SDC2, VVL of SDC1, and GSL II of MEC2 were stained only in tumor cells but not in vascular endothelial cells." (PMID 40844495, 2025). "As with SDC2 and GPC5, expression was not influenced by the location of the tumor, suggesting that this is another common feature shared by all neoplasms, wherever they are in the body." (PMID 24570896, 2014). "Neither Syndecan-2 nor CD44v3 have been extensively studied in EOC, however data from other tumor types is consistent with our preliminary findings and hypothesis." (PMID 22583667, 2012).